MYC (MYC proto-oncogene, bHLH transcription factor)
Diseases named in the same sentence as MYC in open-access papers (continued):
Sharing a sentence is not in itself a finding about the gene and the disease.
cancer (continued). "To investigate whether overexpression of MYC increases the sensitivity of cancer cells to DDAs, we engineered MCF10A human mammary epithelial cells to overexpress EGFR, MYC, or both proteins using retroviral vectors." (PMID 31839995, 2019). "Currently, the mechanism of action of PVT1 in cancer and the interaction mechanism with MYC are not completely clear; however, in-depth studies of PVT1 can contribute to the development of new therapeutic targets." (PMID 31309249, 2019). "However, MYC amplification, that frequently occurs in cancers, is a potential genetic alteration leading to LAT1 overexpression since c-MYC was shown to enhance LAT1 promoter activity in vitro." (PMID 31100853, 2019). "On the contrary, MYC and FOSL1 are restricted to cancer cells." (PMID 31438567, 2019). "In this review, we summarize the coamplification of PVT1 and MYC in cancer, the positive feedback mechanism, and the latest promoter competition mechanism of PVT1 and MYC, as well as how PVT1 participates in the downstream signaling pathway of c-Myc by regulating key molecules." (PMID 31309249, 2019). "In stark contrast, proscillaridin A failed to downregulate more than one KATs in low MYC expressing cancer cells (SW48, A549 and RASV12 transformed fibroblasts)." (PMID 31196146, 2019). "In Jurkat (T-ALL) and K562 (CML) cells, cancer-specific SE with diverse size and location has been proved to interact with a conserved CCCTC-binding zinc-finger protein (CTCF) binding site located 2 kb upstream of the MYC promoter and activate MYC expression." (PMID 31311566, 2019). "Transgenically controlled overexpression of potential culprit genes in mice, including overexpression of MYC and HER2, was important in providing the first experimental evidence that oncogene overexpression alone could induce the formation of malignant tumors." (PMID 31304632, 2019). "It has been documented that various transcriptional factors, such as STAT3, MYC, p65 and BRD4, could directly bind to the promoter of PD-L1 and regulate the transcription of PD-L1 in cancer cells." (PMID 30709380, 2019). "While the concept of SL-MYC-based cancer therapy is alluring based on MYC’s overexpression across many cancer types, most currently available pharmacological or biological agents with proven SL-MYC activity are not suitable for testing in the clinic." (PMID 30728358, 2019). "Given that this pathway operates at the posttranscriptional levels, these cancers would not display altered levels of MYC transcript but will be characterized by the increased expression of downstream MYC targets." (PMID 30635567, 2019). "Sequences encoding G4s are enriched in regulatory regions consistent with roles in transcription and RNA regulation, and their over-representation in oncogene promoters, such as MYC, KRAS and KIT, suggests that they are important in cancer and are potential therapeutic targets." (PMID 31287417, 2019). "By binding with c-MYC, BIN1 could significantly inhibit proliferation and apoptosis ability while induce apoptosis of cancer cells." (PMID 31496920, 2019). "In our work, we think that MYC can be regulated by both METTL3/IGF2BP2 axis and SOX2 respectively, which might partially explain the elevated expression of MYC in various human cancers." (PMID 31230592, 2019). "In addition, MYC has also been connected to the CDK4/6 and that way to CCND1 through these cancer studies." (PMID 30976209, 2019). "Likewise, the miR-376a target genes MYC, NRP1 (Neuropilin-1), and PDIA6 (Protein Disulfide Isomerase Family A Member 6) play crucial roles in cancer-related processes." (PMID 31847321, 2019).
cancer (continued). "In several cancers, including HNSCC, the expression of glucose transporter 1 (GLUT1) is often elevated, and in conjunction with enhanced mTOR signalling (mTORC1 and C2), the pair activates key oncogenic drivers, including c-MYC and HIF-1α." (PMID 30970654, 2019). "Note however, that in the absence of experimental perturbations, both MYC-Low and MYC-High cells executed mitosis successfully, and indeed, both cancers and established cancer cell lines display a wide range of MYC expression." (PMID 31455158, 2019). "Future development of drug candidates inhibiting TOX–DNA interactions could follow previous studies where SMIs have been successfully developed via CADD to target the DNA-binding domains of other cancer drug targets, such as AR, ERG, and MYC." (PMID 31554191, 2019). "The MYC family oncogenes (MYC, MYCN, and MYCL) contribute to the genesis of many human cancers." (PMID 31452837, 2019). "miR-34a inhibits cancer stemness via targeting CD44; miR-34a expression inhibits TGF-β-induced EMT and downregulates Snail, Slug and ZEB1 as well as the stemness factors (BMI1, CD44, CD133, OLFM4 and c-MYC)." (PMID 30885232, 2019). "To identify drugs that could enhance the apoptotic effect of BCL-2/BCL-XL inhibition, while still preserving MYC-dependence, we analyzed the effect of ABT-737 in combinations with small-molecules that target cancer survival pathways." (PMID 30728358, 2019). "Despite the well-established role of MYC protein in driving cancer cell growth, no direct MYC-targeted therapeutic agent has advanced to the clinical setting for DHL and THL DLBCLs." (PMID 31288832, 2019). "Further, our work demonstrates that targeting other signaling pathways that regulate MYC22–24, or targeting MYC, itself, may be a promising approach to overcome de novo BET bromodomain inhibitor resistance and to treat MYC-driven cancers." (PMID 30846826, 2019). "Furthermore, downstream signal-dependent transcription factors activated by PI3K/AKT/mTOR signaling, such as MYC and NRF1, stimulate transcription of cell proliferation and metabolic genes allowing cancer cell growth." (PMID 31315653, 2019). "Although the increasing number of mechanisms of action for PVT1 and its interaction with MYC in cancer are being discovered, there is no application for PVT1 in clinical treatment to date, and only one clinical trial on PVT1 is recruiting subjects." (PMID 31309249, 2019). "In some metastatic and cancer stem cells (bladder, colon, lung, and breast carcinomas), phosphorylated STAT3 (pSTAT3) promotes cancer proliferation by upregulating antiapoptotic proteins (BCL-2, BCL-xl), pluripotency markers (OCT4), and proto-oncogenes (MYC)." (PMID 31600993, 2019). "In other cancer models, CIP2A promoted MYC protein levels in both of the studied AML cell lines." (PMID 31717978, 2019). "Considering the tumorigenic role of c-MYC in diverse cancers including GC, we wondered whether HOXC-AS1 could regulate MYC expression in GC cells." (PMID 31870402, 2019). "Taken together, and given the central role of c-MYC in various cancer types, these findings demonstrate that there may be a positive feedback loop between MYC and UPR in cancer, offering opportunities for therapeutic targeting." (PMID 30679434, 2019).
cancer (continued). "More importantly, this ligand showed cytotoxicity against cancer cell lines overexpressing c-MYC but not against human normal cells or primary mouse cells, suggesting reduced side effects based on the G4 selectivity." (PMID 30682877, 2019). "Given its pivotal roles in cancer development, it is not surprising that MYC is one of the best and most studied oncogenes driven by SEs in hematological malignancies." (PMID 31311566, 2019). "In cancer cells, the N-terminal domain of E1A represses MYC transcription through pathways involving targeting of both p300 and TRRAP, as well as inhibition of H3K18 and H4K16 acetylation, at the MYC promoter." (PMID 31121824, 2019). "This chromatin-based signaling cascade provides an additional mechanistic explanation for the rapid down-regulation of gene expression by (+)-JQ1, which functions to displace densely localized BRD4 molecules from transcriptionally activated cancer-promoting genes including BCL2, CDK6, and MYC." (PMID 31157223, 2019). "Furthermore, there is a synergistic effect of positive feedback between MYC and PVT1, which results in increased expression levels of these genes in cancer." (PMID 31309249, 2019). "Alternative, synthetic-lethal MYC-targeting (SL-MYC) approaches aim to exploit MYC-dependent cancer vulnerabilities without directly inhibiting MYC." (PMID 30728358, 2019). "In low grade glioma and subsets of IDH-mutant AML cases in which the presence of 2HG leads to a more benign outcome, we suggest that 2HG contributes to cancer initiation via inhibiting TET2, but suppresses cancer progression/proliferation via inhibiting FTO/MYC signaling." (PMID 29686311, 2018). "LAT1 not only supports mTORC1 activity, it also reinforces MYC and EZH2 signaling in cancer cells." (PMID 30103560, 2018). "Both PVT1 and c-Myc are located at the same chromosomal location (8q24.21) and an increase in PVT1 expression is required for high MYC protein levels in 8q24-amplified human cancer cells." (PMID 29701689, 2018). "The MYC proto-oncogenes (MYC, MYCN, MYCL) have been extensively studied since their discovery in the early 1980’s and they continue to be of great interest as the most commonly deregulated genes in human cancer." (PMID 29799508, 2018). "How these diverse cancer-specific super-enhancers loop long distances to specifically interact with MYC has not been clear." (PMID 29641996, 2018). "MYC activation, which altered pre‐mRNA splicing without the transcriptional regulation of CLKs, rendered cancer cells vulnerable to CLK inhibitors with synergistic cell death." (PMID 29769258, 2018). "MYC, a classic anti-cancer target for which there is no selective small compound inhibitor, seems to be particularly implicated in recent literature describing the anti-cancer effects of EZH2 inhibition." (PMID 29774113, 2018). "MYC and RAS family oncogenes induce the recruitment of leucocytes and lymphocytes, the expression of chemokines and cytokines, and induce the angiogenic switch, which activates transcription factors in the intrinsic pathway of inflammation-induced cancer." (PMID 29636841, 2018). "It would be interesting to determine whether this FGFR3/MYC feedback loop, mediated by AKT and p38, also operates in other types of human cancers expressing FGFR3‐TACC3." (PMID 29463565, 2018). "In our present study, we found that JQ1 had anti-cancer effects through MYC regulation in ccRCC cells; however, these effects were observed regardless of innate MYC expression." (PMID 29796168, 2018). "In other cancer cell lines, it has been shown instead that INI1 contributes to MYC transcriptional activity 21, and that overexpression of the region of INI1 that binds to MYC blocks MYC transcriptional activation." (PMID 30222246, 2018). "In a PGC1α low cancer cell, the oncogenic driver might for instance be activated BRAF, or MYC, based on an inverse relationship between MYC and PGC1α." (PMID 29361779, 2018).
cancer (continued). "MYC is not directly targetable but inhibiting AK with small molecule inhibitors can indirectly inhibits MYC effects in cancer cells." (PMID 30542505, 2018). "In addition, although there is no definitive report regarding the role of ANO1 in the stemness of cancer cells, it is suspected based upon the result that ANO1 induced expression of MYC." (PMID 29416639, 2018). "We deduced that selective arresting of c-MYC promoter via stabilizing G-quadruplex activates a unique crosstalk with E2F-1 and VEGF-A, that concomitantly reduces BCL-2 expression triggering apoptosis in cancer cells." (PMID 30239898, 2018). "Remarkably, until the availability of JQ1 and derivatives, MYC was considered a non-druggable cancer target." (PMID 29899872, 2018). "Therefore CDK9 inhibition prevents productive transcription and is associated with a global reduction in mRNA, including genes, such as MYC and MCL-1, which regulate proliferation and survival of cancer cells." (PMID 29471852, 2018). "Otherwise, oncogenic alterations in genes such as MYC and KRAS could reprogram glutamine metabolism in cancer cells." (PMID 30419950, 2018). "Therefore, similar to other renowned cancer related proteins (e.g. E2Fs, p21, GADD45A, MYC and RUNX1), Trib2 obeys the Goldilocks principle in cancer biology; too little or too much are both pro-tumorigenic." (PMID 29670085, 2018). "The transcription factor c-MYC is a known downstream effector of ERK signaling, which is regulated on the transcriptional level and has a long standing history as one of the most potent oncogenic factors in cancer." (PMID 30001368, 2018). "Other well-known cancer genes such as BRCA1, CHEK2, JUN, and MYC could also be found in the highly interconnected regions of the PPI network." (PMID 29540752, 2018). "Although the miRanda and Targetscan algorithms did not indicate that miR-665 targeted the c-MYC 3’-UTR, we included this region in our analyses, as cMYC dysregulation is a hallmark of cancer." (PMID 30237861, 2018). "Firstly, CDK1 can be the SL partner gene of the cancer genes KRAS and MYC." (PMID 29855504, 2018). "Strikingly, data from 169 cancer cell lines from the Cancer Cell Line Encyclopedia (CCLE) showed that only those lines harboring MYC amplification were significantly more sensitive to T‐025, making amplified MYC a strong biomarker candidate." (PMID 29789342, 2018). "A research in 2011 indicate that oncogenes like KRAS, MYC and BRAF can promote the expression of NRF2 to degrade ROS to make a more reduced intercellular environment, therefore, protects cancer cell from oxidative stress and promote cell proliferation and tumorigenecity." (PMID 29416692, 2018). "Furthermore, we verified that cyclin D1 affects EMT in OCSLCs, whereas in other studies, NANOG and c-MYC were reported to be involved in OCSC regulation and acted as cancer stem related-markers." (PMID 30518424, 2018). "The rs6983267 SNP may contribute to the increased MYC expression as well as the spread and rapid growth of cervical SCC as compared to lower grade carcinomas." (PMID 29525942, 2018). "The MYC oncogene, which represents a highly validated and studied oncogenic cancer target, has no approved therapies that directly target the protein." (PMID 28205554, 2017). "Our data suggest a crosstalk of NMU signaling with several cancer-relevant pathways including the WNT receptor cascade resulting in an increased activation of the WNT/PCP effector RAC1 as an indicator for enhanced cancer cell motility and down-regulation of the canonical WNT target MYC among others." (PMID 28423716, 2017). "The aRNA significantly inhibited the expression of MYC in mRNA and protein levels, as well as the proliferation and migration of the cancer cells, but not in HFF cells." (PMID 29084575, 2017).
cancer (continued). "The MYC module in one study significantly over-represents the cancer-activated ESC-like module (P < 2e-16, OR = 10), but not the core ESC nor the PRC module in the other study." (PMID 28246384, 2017). "Moreover, it is also well-documented that MYC represses genes involved in cell-cell contact, to induce epithelial-mesenchymal transition (EMT) and enhance metastasis of cancer cells." (PMID 28464854, 2017). "MYC is an oncogene that is expressed in a number of cancer models, but therapies that target MYC directly are not clinically available." (PMID 28362357, 2017). "Our findings support the idea that treatment of KRAS-driven NSCLC and CRC, and potentially the other mutant KRAS driven cancers, may benefit from the concurrent inhibition of KRAS signaling and MYC." (PMID 28152508, 2017). "A recent study illustrated that some MYC-driven cancers are dependent on PVT1 activity, as PVT1 could stabilize MYC protein levels by preventing MYC phosphorylation." (PMID 29113413, 2017). "Given the challenge of inhibiting KRAS directly and the role of MYC in various aspects of cancer progression, therapy for treating KRAS-driven cancers may also be expected to depend on MYC." (PMID 28152508, 2017). "The ability of c-MYC to promote hepatic tumorigenesis has been demonstrated not only in vitro and in vivo studies, but also in human cancer." (PMID 28422055, 2017). "We therefore sought to examine whether MYC expression correlates with RAS activation status in primary and cancer cell lines." (PMID 28152508, 2017). "Although MYC is an established oncogene, PVT1 is also emerging as a prominent player in cancer." (PMID 29113413, 2017). "In addition, Lin28B silencing in PDAC cells inhibited cell proliferation, cell cycle transition, migration and the EMT and increased the expression of the c-MYC, HMGA2 and KRAS genes, which are targeted by the cancer suppressor miRNA let-7." (PMID 28947981, 2017). "Together, these results show that SIRT1 is triggering MYC target gene expression by inhibiting MXD1 function, which may contribute to cancer phenotype acquisition." (PMID 29383100, 2017). "Given that we have observed that diverse genomic and transcriptomic disturbances dysregulated the same signaling pathway and MYC oncogenes frequently played as critical regulators, we concluded that a linkage exists between the two HR-NB prognostic GSPs and the ESC-like cancer signature in HR-NB." (PMID 28984200, 2017). "Given the previously established role of MYC and ODC1 promoter activity it is likely that these DNA copy number gains contribute to the increased ODC activity in these particular cancers especially high grade cancers where DNA copy number change is more frequently present." (PMID 29240775, 2017). "Indeed, TFs such as ESR1, NOTCH1, MYC, GATA3, and ERG, among many others, are frequently aberrantly activated in cancer." (PMID 29023443, 2017). "Hi-MYC mice develop PIN as early as 2 weeks of age and progress to macroscopic cancer by 6 months." (PMID 28978058, 2017). "Conversely, multiple oncogenic signals, including RAS and MYC, can generate metabolic stress and AMPK may promote cancer cell survival under these conditions." (PMID 28872614, 2017). "Despite numerous articles on the subject, it is still not clear how MYC and its regulatory network are promoting such entirely different processes in cancer." (PMID 28333115, 2017).